FUS (FUS RNA binding protein)
Diseases named in the same sentence as FUS in open-access papers (continued):
Sharing a sentence is not in itself a finding about the gene and the disease.
sarcoma (continued). "Our optimized method achieved 100% concordance for the HER2 FISH NordiQC - Quality Control 2015 evaluation, 100% concordance for genotyping and clerical accuracy for the sarcoma panel containing CHOP (DDIT3), FUS, EWSR1 and MDM2 in the UK NEQAS International Quality Expertise 2016 evaluation." (PMID 31236139, 2019). "FUS, EWS, and TAF15 are structurally similar multifunctional proteins that were initially discovered in the process of characterization of fusion oncogenes in human sarcomas and leukemias." (PMID 30087896, 2018). "FUS, EWS, and TAF15 form the FET family of RNA-binding proteins whose genes are found rearranged with various transcription factor genes predominantly in sarcomas and in rare hematopoietic and epithelial cancers." (PMID 21197473, 2011). "Therefore, although EWSR1/FUS::NFATC2 sarcoma has a relatively specific FISH presentation, when diagnosing tumors with EWSR1/FUS::NFATC2 gene rearrangement, it is necessary to consider factors such as the clinical presentation, histological changes, treatment and prognosis." (PMID 38254207, 2024). "In summary, while FUS::DDIT3 binding caused no extreme effects on the SWI/SNF composition, several paralogs as well as PBAF and GBAF subtype-specific components were significantly enriched in FUS::DDIT3-bound SWI/SNF complexes, at levels that may impact the SWI/SNF function in FET sarcoma cells." (PMID 40988026, 2025). "The most common representative of these non-ETS GF entities is EWSR1::NFATC2 or FUS::NTAC2 sarcoma, followed by EWSR1::PATZ1 sarcoma." (PMID 38339014, 2024). "The subgroup of myoepithelioma-like sarcomas was further investigated with regard to the status of the EWSR1 and FUS loci; however, no rearrangement was found." (PMID 22588017, 2011). "We report five patients with EWSR1/FUS::NFATC2-rearranged neoplasms, including one simple bone cyst (SBC), two complex cystic bone lesions lacking morphological characteristics of SBC, and two sarcomas." (PMID 36555836, 2022). "Interestingly, FUS::DDIT3 expression unified the cells into overlapping branches regardless of if sarcoma cells were grown in MLS scaffolds or as xenografts in mice, demonstrating that FUS::DDIT3 expression more than microenvironment determines the transcriptional profile of individual tumor cells." (PMID 38671504, 2024).
liposarcoma (69 papers, 2008 to 2025). A usually painless malignant tumor that arises from adipose tissue. "Originally identified as a gene involved in chromosomal translocation in liposarcoma, the human FUS gene encodes a RNA/DNA binding protein involved in multiple cellular processes." (PMID 26335776, 2015). "Although little is known about its pathogenesis, mutations in fused in sarcoma/translated in liposarcoma (FUS) are causative for familial ALS." (PMID 23577159, 2013). "FUS is a ubiquitously expressed, 526 amino acid protein that was initially identified as a proto-oncogene, and which causes liposarcoma due to chromosomal translocation." (PMID 22724023, 2012). "Shortly after the discovery of TARDBP mutations, mutations in FUS, which encodes the nuclear protein fused in sarcoma (FUS) (also known as translated in liposarcoma, TLS), were identified in a subset of individuals with ALS, and FUS was revealed to be mislocalized to the cytoplasm." (PMID 28468937, 2017). "Recent evidence also shows that aggregation-related mutations in the RBPs Tar DNA-binding protein 43 TDP-43 and Translocated in liposarcoma protein FUS are associated with the formation of RNA granules that are phase separated, non-membrane-bound ribonucleoprotein aggregates." (PMID 26673865, 2015). "Myxoid liposarcoma (MLS) accounts for 20%-30% of all liposarcomas, with most cases harboring the fusion gene FUS::DDIT3, while approximately 5% exhibit the EWSR1::DDIT3 fusion." (PMID 41108625, 2025). "FUS, also known as translocated in liposarcoma (TLS), is a member of the TET (TAF15, EWS, and TLS) family of RNA-binding proteins." (PMID 38542501, 2024). "The Fused in Sarcoma (FUS) protein, also known as Translocated in Liposarcoma (TLS), is a 526-amino-acid-residue RNA-binding protein ubiquitously expressed and encoded by the FUS gene located in 16p11.2." (PMID 39201350, 2024). "As a result, FUS expression in CHOP transgenic mice restored liposarcoma development, indicating that the FUS and CHOP domains cooperate in mutual liposarcoma restoration." (PMID 38002306, 2023). "It is one of Translocated in liposarcoma, Ewing’s sarcoma and TATA-binding protein-associated factor 15 (TET, also named as FET) protein family members that also contains Fused in Sarcoma (FUS) and TATA-box binding protein Associated Factor 15 (TAF15)." (PMID 36230245, 2022). "Fused in sarcoma (FUS, also referred to as translocated in liposarcoma) is a member of the FET (FUS, EWSR1, and TAF15) family of RNA- and DNA-binding proteins that play important roles in transcription and splicing." (PMID 34375640, 2021). "Fused in sarcoma (FUS)/Translocated in Sarcoma (TLS) was first identified as a fusion oncogene in human liposarcomas, which is composed of the FUS residues 1–266 fused with a transcription factor C/EBP Homologous protein (CHOP)." (PMID 31188823, 2019). "Such rearrangement is common in liposarcomas, thus FUS also goes by the name TLS (translocated in liposarcoma)." (PMID 29547565, 2018). "FUS was initially identified as an oncofusion protein in human liposarcomas and later in other cancers where chromosomal rearrangements paired the FUS transactivation domain with transcription factors such as CHOP, CREB3L2, and ERG." (PMID 28762175, 2017). "When FUS-CHOP was silenced in the two myxoid liposarcoma cells, up to 60% growth inhibition occurred." (PMID 27822137, 2016). "By contrast, the FUS-CHOP-negative liposarcoma line SW872 exhibited an IC50 of 25 μM, indicating that these cells were not sensitive to the agent." (PMID 27822137, 2016). "Similar results were seen in a mouse model of liposarcoma, where FUS -CHOP was able to induce liposarcoma genesis in MSCs, whereas no liposarcoma was formed when FUS-CHOP gene was manipulated to be only expressed in differentiated, aP2-expressing adipocytes." (PMID 23880362, 2013).
liposarcoma (continued). "In terms of genetic abnormalities, MRC liposarcoma is characterized by translocation of chromosomes 12 and 16 (t12;16)(q13;p11), that results in a fusion gene arrangement between FUS and CHOP/DDIT3." (PMID 24216990, 2013). "This family of proteins includes: FUsed in Sarcoma (FUS)/Translocated in LipoSarcoma (TLS), EWig's Sarcoma protein (EWS), and the TATA binding Protein-Associated Factor, TAF15." (PMID 21909421, 2011). "This oncogene consists of the NH2-terminal domain of FUS (previously termed translocated in liposarcoma, TLS) fused to the entire codifying sequence of DDIT3 (previously termed CHOP)." (PMID 18596980, 2008). "Notably, the FUS::DDIT3 fusion gene, a common chromosomal translocation in liposarcoma, encodes a transcription factor essential for adipocyte differentiation." (PMID 39229483, 2024). "PPARγ is under the repressive control of the FUS-CHOP fusion oncogene in mixoid liposarcoma." (PMID 36119484, 2022). "In liposarcoma, a chromosomal translocation leads to the fusion of two genes, FUS and UPR-regulated CCAAT/enhancer-binding protein homologous protein, resulting in the synthesis of a chimeric protein that acts as a transcription factor enhancing cell proliferation and promoting tumour progression." (PMID 32987654, 2020). "For example, FUS is involved in the chimera FUS-CHOP in liposarcomas." (PMID 29416553, 2018). "The negatively charged pADPr polymers recruits a large spectrum of proteins, including FET (FUS [fused in liposarcoma], EWS [Ewing sarcoma] and TAF15 [TATA binding associated factor 15]) family proteins FUS and TAF15 that rapidly accumulate at DNA lesions induced by micro-irradiation." (PMID 30456359, 2018). "In case of translocated in liposarcoma (TLS) protein, also known as fused in sarcoma (FUS) protein (TLS/FUS) the mutation of tyrosine residues adjacent to RGG-domain to phenylalanine completely shifted the binding specificity of RGG-domain from RNA to DNA G-quadruplex." (PMID 30247678, 2018). "Overexpression of FUS is observed in liposarcoma and leukemia with FUS translocations." (PMID 24204307, 2013). "Mechanistic studies have demonstrated that trabectedin may have target specificity in MRC liposarcoma by direct interaction with the FUS-CHOP fusion protein, preventing its binding to transcriptional promoters and restoring normal lipoblast maturation." (PMID 24216990, 2013). "Mutations in several genes are causative for FALS, including fused in sarcoma/translated in liposarcoma (FUS), superoxide dismutase-1 (SOD1), TAR DNA-binding protein (TARDBP), angiogenin (ANG), vesicle-associated membrane protein B (VAPB), optineurin (OPTN), and valosin-containing protein (VCP)." (PMID 23577159, 2013). "Moreover, the N-terminal domain of FUS, which was identified as the transcriptional activator in FUS-CHOP and FUS-ERG fusion proteins in liposarcoma and myeloid sarcoma respectively, was recently shown to be sufficient to contact the SWI/SNF chromatin remodelling complex." (PMID 34233002, 2021). "Because the FUS NTD is an independent unit sufficient for initiating liposarcoma development even by separate expression with CHOP, this finding might offer a clue for future in vivo investigation to assess whether LLPS is also involved in its pathological activity." (PMID 31188823, 2019). "Within the realm of liposarcoma research, Pèrez-Mancera’s group generated CHOP and FUS ± CHOP transgenic mice, by introducing CHOP or the FUS-CHOP transgene into mouse genomes." (PMID 38002306, 2023). "The hnRNP P2 as the RBP fused in sarcoma/translocated in liposarcoma (FUS/TLS), is also called FUS, which mutants often be reported to relate to cancer and neurodegeneration in humans." (PMID 34796209, 2021). "The protein called fused in sarcoma (FUS; also known as translocated in liposarcoma; TLS) was first identified in human myxoid liposarcomas ~30 years ago, suggesting that this protein plays a critical part in cancers." (PMID 32987654, 2020).
liposarcoma (continued). "Previously, translocated in liposarcoma (TLS) protein, also known as fused in sarcoma (FUS) protein, was found to form a ternary complex with the G-quadruplex structures of telomeric DNA and TERRA." (PMID 29434328, 2018). "Other tumor-specific fusion genes, such as EWS-CHOP and TLS/FUS-CHOP, have been detected in solid tumors and liposarcomas." (PMID 19558691, 2009). "In addition to being a diagnostic utility, detection of MDM2 amplification and CHOP rearrangement impact liposarcoma treatments that use selective MDM2 inhibitors and blockers of trans-activating ability of FUS-CHOP fusion protein." (PMID 29531545, 2017). "Approximately 50% of myxoid liposarcoma cells express nuclear FUS-CHOP, and cells that are negative for CHOP express high levels of proliferation markers." (PMID 27822137, 2016). "The FUS gene was originally identified in a study that found that the FUS protein forms part of a fusion protein with the transcription factor CHOP, which arises due to a chromosomal translocation in liposarcoma." (PMID 22724023, 2012). "Introduction of FUS-CHOP into mice, where expression of the transgene is driven by the ubiquitously expressed elongation factor 1α (EF1α) promoter, results specifically in liposarcomas with inherent induction of adipocyte specific genes such as PPARγ." (PMID 21253554, 2011). "Notably, no DDIT3 or FUS gene rearrangements were detected, prompting the classification of the sarcoma as a dedifferentiated liposarcoma." (PMID 39229483, 2024). "Fused in Sarcoma/Translocated in Liposarcoma (FUS/TLS) belongs to the FET (FUS- EWSR1, TAF15) family protein and was described for the first time in myxoid liposarcoma as an oncogenic fusion of the dominant negative transcription factor gene CHOP with the gene FUS." (PMID 34299185, 2021). "Interestingly, the FUS NTD represents an independent unit to fuse with CHOP with the DNA-binding domain to form an aberrant transcription factor TLS/FUS-CHOP, in which the FUS NTD is absolutely required for oncogenesis because the overexpression of only CHOP did not develop liposarcoma." (PMID 31188823, 2019).
Ewing sarcoma (65 papers, 2008 to 2026). A small round cell tumor that lacks morphologic, immunohistochemical, and electron microscopic evidence of neuroectodermal differentiation. "In the present study, a Ewing's sarcoma patient with both FUS-ERG fusion and CDKN2A/B loss was studied." (PMID 27286459, 2016). "FUS is a 526 amino acid DNA/RNA binding protein member of the FET family (FUS/Ewing’s sarcoma/TATA-binding protein-associated factor)." (PMID 23046583, 2012). "Ewing sarcoma is a small round-cell sarcoma characterized by gene fusion involving EWSR1 (or another TET family protein like FUS) and an ETS family transcription factor." (PMID 39158802, 2025). "Other Ewing sarcoma cases are caused by alternative ETS protein fusions, including EWS‐ERG, EWS‐ETV1, EWS‐ETV4, EWS‐ETV5, EWS‐FEV, FUS‐FEV, and FUS‐ERG." (PMID 40285687, 2025). "The translation of the ERG gene gives rise to different fusion gene products, such as TMPSSR2-ERG and NDRG1-ERG in prostate cancer, EWS-ERG in Ewing’s sarcoma, and FUS-ERG in acute myeloid leukemia." (PMID 36009466, 2022). "Ewing Sarcoma (ES) is a primitive small round cell sarcoma defined by fusions involving members of the FET (predominantly EWSR1 or FUS) and ETS (most commonly including FLI1, ERG, ETV1, ETV4, or FEV) gene families." (PMID 35059992, 2022). "This gene was fused with chromosome 16 FUS or chromosome 22 EWSR 1 to produce a chimeric protein in myxoid liposarcoma or Ewing's sarcoma." (PMID 34754325, 2021). "A total of 13/31 (42%) of the MN-NE showed EWSR1-related gene fusions (6 Ewing sarcomas, 5 clear cell sarcomas, and 1 desmoplastic small round cell tumor, 1 neoplasm with FUS-CREM gene fusion) and 7 (23%) were SWI/SNF (SMARCB1 or SMARCA4)-deficient neoplasms." (PMID 34350470, 2021). "We developed a novel RT–PCR assay that can efficiently detect both EWSR1-ETS and FUS-ETS observed in Ewing sarcoma." (PMID 34749732, 2021). "For example, FUS-ERG and FUS-FEV fusions are typically classified as Ewing sarcoma; however, respondents felt much less confident about classifying this as Ewing sarcoma in comparison to other rare EWSR1-FLI1-related gene variants." (PMID 33488267, 2020). "The FET protein family, which includes FUS (Fused in Sarcoma), EWG (Ewing Sarcoma) and TAF15 (TATA binding association factor 15) proteins, is a group of RBPs containing three different long IDRs characterized by the presence of RGG motifs." (PMID 33262375, 2020). "In this study, by employing multiple approaches, we have now identified several splicing factors (SRSF1, SRSF3, and SRSF10, hnRNPK, hnRNPM, and FUS) as regulators of DHX9 splicing in Ewing sarcoma cells." (PMID 32023846, 2020). "For example, it fuses with TMPRSS2 in most prostate cancers, with EWS in Ewing’s sarcoma, and with FUS in AML." (PMID 30736820, 2019). "This is consistent with the results of the present study that targeting the IGF-IR inhibited the Ewing sarcoma PDOX with the FUS/ERG fusion." (PMID 27286459, 2016). "Fusion of ATF1 with the Ewing’s Sarcoma gene, or with FUS, results in continuous signaling and sarcomatous tumour formation." (PMID 26553438, 2015). "FUS, together with EWS (Ewing's sarcoma) and TAF15 (TBP-associated factor 15) in vertebrates, belongs to the FUS/EWS/TAF15 (FET) or TLS/EWS/TAF15 (TET) family." (PMID 26150427, 2015). "FUS knockdown also correlated with increased expression of the closely related protein EWS (Ewing's sarcoma)." (PMID 25501833, 2014). "Comparing with the understanding of EWS and FUS functions, roles of abnormal chimeric proteins fused by EWS/FUS and ETS family genes that cause Ewing sarcoma are better characterized in stem cell biology." (PMID 23984388, 2013). "The same fusion FUS/ERG has also been found in 3 Ewing tumors; it is thus one of the relatively few fusion genes that exert pathogenetic influence in widely disparate neoplastic entities." (PMID 24068373, 2013). "Identifying an EWSR1/FUS::FLI1 gene fusion is pivotal in confirming Ewing’s sarcoma." (PMID 40860805, 2025).